EBI3 (Epstein-Barr virus induced 3)
Diseases named in the same sentence as EBI3 in open-access papers (continued):
Sharing a sentence is not in itself a finding about the gene and the disease.
Chagas disease (2 papers, 2017 to 2025). A parasitic infection caused by Trypanosoma cruzi. "In addition, polymorphic sites at Ebi3 gene were associated with severe cardiomyopathy in patients with Chagas disease." (PMID 29033934, 2017). "Indeed, polymorphic sites at Ebi3 gene in Chagas disease patients were associated with more severe forms of CCC, suggesting that IL-27 may have a protective effect on the pathogenesis of the human disease." (PMID 29033934, 2017). "In summary, Ebi3 has a broad spectrum of suppressive functions that help to maintain tissue integrity, even during the chronic stage of Chagas disease." (PMID 29033934, 2017). "Collectively, our data support Ebi3 as a novel regulatory immune-modulator that prevents cardiomyopathy, thus opening a reasonable perspective for the therapeutic manipulation of Ebi3 that could be useful for patients with Chagas disease." (PMID 29033934, 2017). "To confirm the importance of IL-27 in Chagas disease and understand whether polymorphic sites at Ebi3 gene might contribute to the severity of the disease, we assessed whether the two most prevalent polymorphic regions at the Ebi3 gene were related to the clinical manifestations of Chagas disease." (PMID 29033934, 2017). "EBI3/IL-27B dampens IFN-γ driven inflammation by inducing IL-10-producing Tr1 cells, and plasma levels of EBI3/IL-27B are higher in indeterminate/ASY Chagas disease patients than CCC patients." (PMID 40297326, 2025).
colon cancer (2 papers, 2022). "In good accordance with the generally suggested immunosuppressive and tumor-promoting function of IL-35, the overall increased presence of the two IL-35 subunits p35 and EBI3 in colon tumor tissue reached the most pronounced expression levels in advanced and poorly differentiated colon tumors." (PMID 36428508, 2022).
coronary artery disease (2 papers, 2012 to 2017). "The aim of the present study was to establish if the polymorphisms of IL-12A and EBI3 genes that encode the IL-35 subunits are associated with the development of premature coronary artery disease (CAD) in Mexican individuals." (PMID 28321150, 2017).
COVID-19 (2 papers, 2023 to 2025). A disease caused by infection with severe acute respiratory syndrome coronavirus 2. "While the expression of IRF1 was significantly increased in PBMCs from patients with severe or critical COVID-19, its expression in monocytes was increased only in patients with severe COVID-19, as was observed with IL27p28 and EBI3." (PMID 37310504, 2023). "Transcriptomic analysis showed that the expression of both IL27 subunits – IL27p28 and EBI3 – increased with severity of COVID-19 in both PBMCs and monocytes (respectively)." (PMID 37310504, 2023).
experimental autoimmune encephalomyelitis (2 papers, 2021 to 2023). An autoimmune demyelinating disease of the central nervous system that is produced experimentally in animals by the injection of homogenized brain or spinal cord in Freund's adjuvant. "In mice with B cell-specific p35 (p35-/-) or EBI3 (Ebi3-/-) deficiency, exacerbated experimental autoimmune encephalomyelitis (EAE) was developed, indicating that IL-35-producing Breg cells restrain the pathogenesis of EAE." (PMID 34168653, 2021).
Granuloma (2 papers, 2014 to 2020). A compact, organized collection of mature mononuclear phagocytes, which may be but is not necessarily accompanied by accessory features such as necrosis. "Correlation analysis among the expression of TET1, 2 and 3 and DNMT1, 3A and 3B indicated that there was a negative correlation between DNMT1 and TET3 gene expression and granuloma number in EBi3-/-I." (PMID 32078636, 2020). "The number of granulomas in livers of WTI mice (median = 57.5) was significantly higher than that in EBi3-/-I mice (median = 22), with p = 0.0001." (PMID 32078636, 2020). "EBi3-/-I mice show decreased hepatic damage considering volume and reduced number of granulomas compared to WTI mice; the absence of IL27 and IL35 pathways decreases the Th1 response resulting in minor liver damage." (PMID 32078636, 2020). "In this work it was observed that there is a negative correlation between this miRNA and the DNA methyltransferase and demethylase genes (DNMT1 and TET3) and positive with the number of granulomas found in the liver of EBi3-/-I mice, which does not occur in WTI." (PMID 32078636, 2020). "In this study, the absence of IL27 due to EBi3 knockout could also have triggered a decrease in IFNɣ and a decrease in granulomas volume, since this cytokine is important in the acute phase of schistosomiasis." (PMID 32078636, 2020).
Hepatic fibrosis (2 papers, 2019 to 2023). The presence of excessive fibrous connective tissue in the liver. "Interestingly, higher level of both IL-35 subunits EBI3 and p35 was positively associated with the degree of hepatic inflammatory and the stage of hepatic fibrosis in AIH patients." (PMID 31787974, 2019). "We investigated the relationship between the expression of EBI3 and the expression of liver fibrosis markers and HSC activation markers." (PMID 37480105, 2023). "GO (Gene Ontology) and KEGG (Kyoto Encyclopedia of Genes and Genomes) pathway analyses were performed to investigate the potential role of EBI3 in liver fibrosis by regulating the extracellular matrix structural constituent and collagen catabolic process." (PMID 37480105, 2023). "We first established a mouse model of liver fibrosis induced by C. sinensis infection and then measured the serum expression of EBI3 during the inflammatory and fibrotic phase." (PMID 37480105, 2023). "However, it remains unknown whether EBI3, a downstream target of Foxp3+ Treg cells, plays a role in mediating HSCs activation and regulating the development of liver fibrosis." (PMID 37480105, 2023). "In order to further study the mechanism of EBI3 in the formation of liver fibrosis, we performed GO and KEGG pathway analysis to predict the function of EBI3." (PMID 37480105, 2023). "In the GSE55747 database, we found that EBI3, COL1A1 and COL3A1 mRNA expressions in mice of the liver fibrosis group were also higher than those of the normal group." (PMID 37480105, 2023). "Moreover, we explored the potential of recombinant EBI3 (rEBI3) in inhibiting HSC activation and reducing liver fibrosis induced by C. sinensis in vitro and in vivo." (PMID 37480105, 2023). "However, the increased expression of serum EBI3 can promote the high expression of gp130 in HSCs, activating the JAK1/STAT3 pathway, which in turn inhibits the expression of ECM and leads to attenuated liver fibrosis." (PMID 37480105, 2023).
hepatocellular carcinoma (2 papers, 2016 to 2019). A malignant tumor that arises from hepatocytes. "When we stained serial sections of non-neoplastic reactive lymph nodes (n = 6) and of a case of hepatocellular carcinoma with 2G4H6 anti-EBI3 mAb or 15k8D10 mAb, we observed a discordant pattern of staining between both mAbs." (PMID 31316915, 2019).
liver cirrhosis (2 papers, 2017 to 2023). "Due to lack of commercial antibody to IL-35 several years ago, previous study showed the increase in both mRNA and protein level of EBI3 in patients with hepatitis B associated liver cirrhosis, which indicated the involvement of IL-35 in the pathogenesis of HBV related liver diseases." (PMID 29181338, 2017). "Previous studies have reported that the expression of EBI3 in the serum of patients with liver cirrhosis is reduced." (PMID 37480105, 2023). "Clinical studies have suggested that EBI3 expression is decreased in the serum of patients with liver cirrhosis." (PMID 37480105, 2023).
liver diseases (2 papers, 2017 to 2019). "We found that the expression of EBI3 was significantly higher in patients with AIH than that in healthy controls and patients with other liver diseases." (PMID 31787974, 2019).
lymphoma (2 papers, 2011 to 2013). A malignant (clonal) proliferation of B- lymphocytes or T- lymphocytes which involves the lymph nodes, bone marrow and/or extranodal sites. "In these lymphomas, an inverse correlation between EBI3 and c-myc expression was observed (n = 194, p = 0.0007)." (PMID 21931777, 2011). "Collectively, these data suggested that EBI3 expression level could be indicative of the level of c-myc expression and could constitute a marker to identify lymphomas with c-myc translocations, among both BL/DLBCL and DLBCL." (PMID 21931777, 2011). "Indeed, we observed that lymphomas, other than mBL, harboring myc-translocations had higher expression of c-myc, as expected, but also lower expression of EBI3 (p<0.0001)." (PMID 21931777, 2011).
metastatic melanoma (2 papers, 2013 to 2024). A melanoma that has spread from its primary site to another anatomic site. "Interestingly, comparison of IL-27 staining in primary and metastatic melanoma from the same patient showed that expression of EBI3 and p28 by tumor cells was not downregulated upon tumor progression." (PMID 24130734, 2013).
myocarditis (2 papers, 2017 to 2018). Myocarditis is a condition that is characterized by inflammation of the heart muscle (myocardium). "Here, we showed that Ebi3, a subunit of IL-27, is not only important to ameliorate liver immunopathology, but more broadly it is also essential to suppress myocarditis caused by T. cruzi." (PMID 29033934, 2017). "It not only corroborates the importance of Ebi3 as a regulator of liver immunopathology but it also points out the importance of Ebi3 to modulate myocarditis upon T. cruzi infection." (PMID 29033934, 2017). "In addition, Ebi3 regulated IFN-γ-mediated myocarditis by promoting an anti-inflammatory environment through IL-10, which was most likely produced by Tr1 cells rather than classical regulatory T cells (Tregs), in the heart tissue of T. cruzi-infected animals." (PMID 29033934, 2017). "We reported that T. cruzi-induced myocarditis was prevented by Ebi3." (PMID 29033934, 2017). "We hypothesized that Ebi3 is required for the induction of an anti-inflammatory environment and controlling of T. cruzi-induced myocarditis." (PMID 29033934, 2017). "Based on our earlier findings that Ebi3 could attenuate inflammatory intensity by inducing Tr1 cells after T. cruzi infection, we evaluated whether the treatment of T. cruzi-infected Ebi3-deficient mice with anti-IFN-γ MAb could control myocarditis and improve host survival." (PMID 29033934, 2017). "It was recently described using Ebi3 deficient mice (C57BL/6 background) infected with the Y strain, that Ebi3 modulates IFN-γ mediated myocarditis, through IL-10, likely produced by Tr1 cells rather than classical Treg cells." (PMID 29545782, 2018).
nasopharyngeal carcinoma (2 papers, 2016 to 2022). A carcinoma arising from the nasopharyngeal epithelium. "In addition, although IL-12p35 positive expression was associated with a worse survival in nasopharyngeal carcinoma, multivariate analyses suggested EBI3 rather than IL-12p35 was an independent prognostic marker." (PMID 39291183, 2022).
non-small cell lung carcinoma (2 papers, 2022 to 2025). A group of at least three distinct histological types of lung cancer, including non-small cell squamous cell carcinoma, adenocarcinoma, and large cell carcinoma. "In non-small-cell lung cancer (NSCLC), EBI3 overexpression and elevated circulating IL-35 levels are linked to advanced disease and poor prognosis, suggesting IL-35 reflects tumor burden and may facilitate immune evasion." (PMID 40869939, 2025).
parasitemia (2 papers, 2017 to 2023). "In addition, the bloodstream parasitemia levels in Ebi3-deficient mice were lower compared to WT mice, notably at the peak of the infection (9 d.p.i)." (PMID 29033934, 2017). "However, our study found a lower parasitemia in Ebi3-deficient mice after infection with 1,000 forms of the Y strain of T. cruzi." (PMID 29033934, 2017). "The proportions of CD4+ T cells in peripheral blood (PB) were significantly higher at day 7 and 28 compared to wild‐type (WT) for Ebi3−/− mice and at day 21 for Il‐27−/− mice, although parasitemia levels were comparable." (PMID 37855243, 2023). "In agreement with the importance of IL-27 to the T. cruzi infection, we observed that the gene expression of the subunits p28 and Ebi3 was higher than p35 at the peak of the parasitemia." (PMID 29033934, 2017). "The absence of Ebi3 or IL-27Rα was also associated with a higher parasitemia after the experimental infection with 500 forms of the Tulahuen strain of T. cruzi." (PMID 29033934, 2017). "In addition, neutralization of IL-4 in IL-27Rα-deficient mice or inhibition of Arginase-1 in Ebi3-deficient mice was essential to control the parasitemia, but did not alter the host survival." (PMID 29033934, 2017).
pulmonary fibrosis (2 papers, 2021 to 2023). Chronic progressive interstitial lung disorder characterized by the replacement of the lung tissue by connective tissue, leading to progressive dyspnea, respiratory failure, or right heart failure. "In this study, we used EBI3 knockout (KO) mice to prove that IL-35 inhibits the progression of pulmonary fibrosis, as well as cellular models, and dissected the underlying molecular mechanism." (PMID 34711217, 2021). "In this study, we investigated the pathological role of EBI3 in pulmonary fibrosis and dissected the underlying molecular mechanism." (PMID 34711217, 2021). "Studies have found that EBI3 can alleviates bleomycin-induced pulmonary fibrosis by suppressing DNA enrichment of STAT3." (PMID 37480105, 2023). "Our previous results showed that the expression level of IL-35 subunit EBI3 was significantly increased in pulmonary fibrosis tissues induced by bleomycin treatment." (PMID 34711217, 2021). "Hydroxyproline is an important biomarker for pulmonary fibrosis, which increased in the lung tissues of bleomycin exposed mice, and the highest hydroxyproline level was observed in EBI3 KO mice." (PMID 34711217, 2021). "In comparison with control groups, IL-35 (EBI3) was one of the most up-regulated genes in the lung tissues of bleomycin-induced pulmonary fibrosis mice and patients with pulmonary fibrosis." (PMID 34711217, 2021). "Masson Trichrome staining data showed that there was more pulmonary fibrosis accumulation in EBI3 KO mice relative to that in WT mice, and Ashcroft score of KO mice was significantly higher than WT control." (PMID 34711217, 2021). "In order to further evaluate the pulmonary fibrosis induced by bleomycin, we performed qRT-PCR to analyze the expression of fibrosis-related genes in the lung tissues of WT and EBI3 KO mice." (PMID 34711217, 2021). "A lot of genes were increased in pulmonary fibrosis tissues, and EBI3, a subunit of the cytokine IL-35, was one of highest up-regulated genes." (PMID 34711217, 2021). "Moreover, knockdown of IL-35 subunit EBI3 increased the expression of a variety of fibrosis-related genes and aggravated the symptoms of bleomycin-induced pulmonary fibrosis in mouse model." (PMID 34711217, 2021). "EBI3 knockdown aggravated the symptoms of pulmonary fibrosis in mice." (PMID 34711217, 2021). "In vitro experiments have further revealed that EBI3 may reduce type I collagen expression when co-cultured with fibroblasts and alleviate pulmonary fibrosis induced by bleomycin by suppressing signal transducer and activator of transcription (STAT3) DNA binding." (PMID 37480105, 2023).
rheumatoid arthritis (2 papers, 2011 to 2022). A chronic, systemic autoimmune disorder characterized by inflammation in the synovial membranes and articular surfaces. "The function of the EBi3/p35 heterodimer was not known until relatively recently when studies using a recombinant EBi3/p35 protein in a rheumatoid arthritis mouse model showed that joint inflammation was effectively resolved by the recombinant protein." (PMID 20981280, 2011). "Moreover, EBI3 modulates ER stress sensor inositol-requiring enzyme 1 α (IRE1α) after induced by IL-1β, and MSC-like cells coexpress EBI3 and IRE1α in rheumatoid arthritis (RA) synovial tissue." (PMID 36548354, 2022).
abortion (1 paper, 2025). the ending of pregnancy by removing a fetus or embryo before it can survive outside the uterus. "Therefore, this study aimed to investigate the influence of intraperitoneal administration of recombinant IL-35 (rIL-35) and anti-Ebi3 antibody shortly after mating on successful pregnancy, fetal blood flow, and the profiles of several types of regulatory cells in a murine abortion-prone model." (PMID 41346623, 2025).
airway hyperresponsiveness (1 paper, 2013). "IL-35, a novel heterodimeric cytokine comprised of the IL-12α (p35) and EBV-induced gene product (EBI-3) subunits, has also been associated with high ICOS expressing Treg in a mouse model of airway hyperresponsiveness." (PMID 23967339, 2013).
asthma (1 paper, 2023). "Lung macrophages are essential players in the development of allergic airway diseases such as asthma, where IL-35 (and, thus, possibly IL-12α and/or EBI3) play important roles." (PMID 37878703, 2023).
Candida infection (1 paper, 2021). "Further mechanistic studies are warranted to address the roles of EBI3 and IL-35 in Candida infection in humans using higher patient numbers and appropriate laboratory experiments." (PMID 34209407, 2021). "The pro-inflammatory cytokine, IL-17A, and its regulatory factors of EBI3 and IL-12A (which combine to form the anti-inflammatory cytokine IL-35) are likely to be highly relevant factors in combating Candida infection." (PMID 34209407, 2021). "The findings of this study suggest that both inflammation and immune regulation co-exist within the mucosal tissues of CHC, and that EBI3 may play an important role in the immune regulation of this Candida infection." (PMID 34209407, 2021).
central obesity (1 paper, 2017). "In healthy controls, the EBI3 rs4905 and EBI3 rs4740 were associated with low risk of central obesity and increased risk of high levels of AST, whereas the IL-12A rs583911 correlated with high risk of increased SAT and IL-12A rs568408 with diminished risk of metabolic syndrome." (PMID 28321150, 2017).
cervical cancer (1 paper, 2024). A primary or metastatic malignant neoplasm involving the cervix. "Further, downregulation of EBI3 was seen in cervical cancer tissues following radiotherapy, and the overexpression of EBI3 could play a preventive effect against radiation-induced immunosuppression on cervical cancer cells." (PMID 39726752, 2024).
Chronic colitis (1 paper, 2021). A chronic inflammatory disease of the large intestine (colon, cecum and rectum). "Recently, histone acetylation was shown to regulate the expression of EBI3, as part of the anti-inflammatory IL-12 cytokine family member IL-35 (EBI3/IL-12p35), in noncancerous cells generated from healthy human colon epithelium, as well as in a murine model of DSS-induced chronic colitis." (PMID 34069352, 2021).
chronic hepatitis C (1 paper, 2025). "CD4P/I(hi) T cells also expressed several genes not typical of the Tfh subset, including EBI3, a subunit of the IL-27, IL-35, and IL-39 cytokines, and the inflammatory cytokine IL32 associated with liver injury in chronic hepatitis C." (PMID 40956619, 2025).
Cirrhosis (1 paper, 2020). A chronic disorder of the liver in which liver tissue becomes scarred and is partially replaced by regenerative nodules and fibrotic tissue resulting in loss of liver function. "High HBV DNA is considered major contributing factor in the development of cirrhosis, and further HCC; therefore, we analyzed the association between IL-27p28/EBI3+ TFH with HBV DNA." (PMID 33584666, 2020).
emphysema (1 paper, 2016). "By employing a mouse model of emphysema induced by cigarette smoking, we achieved results similar to COPD patients that not only IL-27 protein but also p28 and EBI3 mRNA expression was notably upregulated in mice after cigarette smoke exposure." (PMID 27994590, 2016).